IL6 (interleukin 6)
Diseases named in the same sentence as IL6 in open-access papers (continued):
Sharing a sentence is not in itself a finding about the gene and the disease.
viral infection (continued). "IL-6 is an acute-phase pro-inflammatory cytokine secreted primarily by macrophages, important for regulating inflammatory disorders such as viral infections." (PMID 40165959, 2025). "ST3GAL2 resists viral infection by downregulating pro-inflammatory cytokines (IL-6, IL-18, IL-1β, IFN-β, TNF-α) and upregulating anti-inflammatory cytokines (IL-4, IL-10, IL-13)." (PMID 40755778, 2025). "IL-6 is produced by airway epithelial cells and various immune cells in response to viral infections and tissue damage." (PMID 40630640, 2025). "Poly(I:C), a synthetic double-stranded RNA used to mimic viral infection, was the most potent stimulator, significantly upregulating IL-6 and IL-8 expression and release." (PMID 40142465, 2025). "In the transcriptome data, Il1b and Ptgs2 (encoding cyclooxygenase 2, COX‐2) showed higher elevation at almost all the time points post viral infection, while some other genes like Il6, Il12b, and Cxcl5 only showed significant elevation at 48 hpi." (PMID 38992966, 2025). "These signaling molecules respond to viral infection by amplifying IL-6 expression, contributing to the inflammatory cascade." (PMID 40309168, 2025). "Viral infections lead to an inflammatory response that includes elevated levels of IL‐6 and interferons." (PMID 39921246, 2025). "Similar reductions were also observed for proinflammatory cytokines Il-6 and Tnfα following viral infection, indicating that MAVS phosphorylation contributes broadly to antiviral cytokine responses." (PMID 40837220, 2025). "Viral infections have been proposed to enhance inflammatory signaling through IL-6, TNF-α, and IFNs, all key players in joint inflammation and autoimmune progression." (PMID 40722700, 2025). "During bacterial or viral infections or under stress, monocytes secrete pro-inflammatory cytokines (IL-1, IL-6, TNF-α)." (PMID 39858269, 2025). "Among many cytokines, the most crucial ones in terms of viral infection are IFNs, IL-8, IL-6, IL-1, granulocyte and macrophage colony-stimulating factor (GM-CSF), TNF alpha, IL-18, IL-12, IL-2, and IL-23." (PMID 40358160, 2025). "TNF-α, IL-1, and IL-6, which are key pro-inflammatory cytokines released by the host during viral infection, were significantly upregulated (fold change >20 compared to the PBS group)." (PMID 40626651, 2025). "Viral infection activates the immune system, leading to the release of inflammatory mediators such as proinflammatory cytokines (IL-6, IL-1β, and TNF-α) and eicosanoids (PG and LT)." (PMID 40580333, 2025). "IL-6 is another key cytokine in chronic FCGS, potentially increasing susceptibility to persistent viral infections such as FCV or FFV (FFV) infections that are directly associated with persistent inflammation and ulceration of the oral mucosa." (PMID 41402880, 2025). "During viral infections such as Influenza A, piezoelectric biosensors have been used to detect cytokines like Interleukin-6 (IL-6)." (PMID 39589620, 2024). "At the same time, lower sgp130, which interacts with the IL-6/sIL-6R complex, leads to a decreased block in IL-6 trans-signalling, thus confirming the reduced antagonistic role of sgp130 during viral infection." (PMID 39063569, 2024). "During acute viral infection, specific effector cytotoxic T -cells (CTLs) secrete IFNγ, which in turn induce the release of hematopoietic cytokines such as IL-6 from bone marrow-mesenchymal stromal cells (MSCs)." (PMID 38965547, 2024). "Its regulation is increased in bacterial infections in response to tumor necrosis factor-alpha, IL-1, and IL-6 and decreased in viral infections by interferon-gamma." (PMID 39724169, 2024). "In contrast to the gene expression data from A549 following AR enzalutamide or siRNA treatment, viral infection induced down-regulation of MAF with up-regulation of IL6." (PMID 38292196, 2024).
viral infection (continued). "In response to viral infection, immune cells secrete various pro-inflammatory cytokines including IL-1, IL-6, interferon (IFN)-γ, and tumor necrosis factor (TNF), shifting the metabolic state toward aerobic glycolysis." (PMID 38965547, 2024). "While IL-6 is vital for viral infection control, its overproduction can lead to hypercytokinemia, increased vascular permeability, and respiratory and multi-organ failure." (PMID 39597537, 2024). "Another macrolide that has had an effect on virus infection is clarithromycin on rhinovirus, which was found to suppress the production of IL-6, IL-1β, IL-8, and granulocyte and macrophage colony-stimulating factor." (PMID 39460768, 2024). "IL-6, a key pro-inflammatory cytokine, is crucial for recovery from multiple viral infections but can be detrimental if overproduced, as it hinders viral clearance and survival." (PMID 39458339, 2024). "These include proinflammatory M1-like macrophages, which produce TNF, IL-1β and IL-6, in the context of both metabolic disease and viral infection." (PMID 39107476, 2024). "Understanding the mechanisms of viral-induced exacerbations and the role of inflammatory mediators like IL-6 is crucial for developing targeted therapies to mitigate the impact of viral infections on chronic lung diseases." (PMID 39458339, 2024). "We investigated the innate immune response after viral infection, and found that Ifnb and Il6 expression was increased by HAZV infection, but did not increase after JEV infection." (PMID 39348382, 2024). "Nevertheless, IL-6 and IL-10 effects in the course of viral infections depend on its spatial and temporal delivery." (PMID 39457019, 2024). "The local expressions of IL1, IL6 and TNFα were reported mainly after the exposure of pigs to a bacterial or viral infection and even in humans in the form of inflammatory bowel diseases." (PMID 39409727, 2024). "Interleukin-6 is one of the key cytokines involved in the host’s immune response during viral infection." (PMID 38255717, 2024). "TLR-3 and TLR-7 closely interact with STAT-3, which is crucial for regulating cytokine-mediated responses, such as IL-6 to combat viral infections." (PMID 39281683, 2024). "IL-6 is a pro-inflammatory cytokine primarily produced during acute and chronic inflammation by macrophages and activated T cells during viral infection." (PMID 39281667, 2024). "Of course, such an intervention would need to be safe, or even beneficial to patients with a virus infection (as IL-6/JAK inhibitors can be), to justify application for the likely millions of cancer survivors who experience respiratory virus infections." (PMID 38645169, 2024). "PCT release is mediated by cytokines that increase in response to bacterial infections, such as tumor necrosis factor-α, interleukin 1β, and interleukin 6, and is suppressed by interferons released in response to viral infections." (PMID 38398159, 2024). "Viral infection induces a variety of proinflammatory cytokines and chemokines including IL-1b, IL-6, TNFa, CCL2, CCL3, CXCL1, CXCL2, CXCL9 and CXCL1034,35." (PMID 38750107, 2024). "Our findings highlight IL-6 as the most promising candidate biomarker for diagnosing viral diseases, with AUC higher than 0.85, surpassing arachidonic acid and CRP." (PMID 39066228, 2024). "With viral infection, IL-6 production increases, along with macrophage activation syndrome, increasing CRP." (PMID 38785752, 2024). "B-cells are important source of cytokines in viral infections, among which IL-6 has potent antiviral activity." (PMID 39445017, 2024). "In fish, interleukin-6 (IL-6) is a very important immune-regulatory cytokine that plays a crucial role in host defense against viral infections." (PMID 39337523, 2024). "It has been noted that IL-6, as an anti-inflammatory cytokine, plays a vital role in viral infection of the respiratory tract." (PMID 38263162, 2024).
viral infection (continued). "The presence of a viral infection and elevated levels of IL-6 demystify the potential etiologies of CD." (PMID 39161530, 2024). "IL-6 production is triggered in response to bacterial and viral infections and other cytokines such as IL-1β, TNF, and IFN-γ." (PMID 38362301, 2024). "Macrophages produce IL-18 at the very early stages of viral infection and induce the production of IL-6 and IFN-γ." (PMID 39273479, 2024). "Since the concentrations of the proinflammatory mediators during fibrosis, cirrhosis, and virus infection are known to increase, the serum concentrations of such cytokines as IL-6 and IL-1 are used to measure the severity of liver disease." (PMID 39769138, 2024). "This systematic review identified that in vitro evaluation of proinflammatory cytokines released by microglia against viral infections, mainly the cytokines IL-6, TNF-α and IL-1β, was frequently compared to the evaluation of anti-inflammatory cytokines." (PMID 38349562, 2024). "Subsequently, there was a proposal to employ IL-6 pathway blockade to manage cytokine release syndrome stemming from virus infection." (PMID 39063569, 2024). "The IL-6 response to viral infection appears to be mediated via NF-kB, whereas its enhancement by cAMP-elevating agents is via a mechanism dependent upon cAMP response element cis-acting sites." (PMID 39598462, 2024). "Measurement of IFN-β and IL-6 levels after virus infection revealed lower levels in B175L-transfected cells than in control cells." (PMID 37902401, 2023). "In the case of viral infections, elevated levels of various inflammatory cytokines, including IL-1β, IL-6, IL-7, IL-17, IFN-γ, IL-8, TNFα, and GM-CSF are observed, alongside IL-4 and IL-5." (PMID 37692890, 2023). "One of the mechanisms proposed to explain the lymphopenia in severe virus infections is the overproduction of IL‐6 driving the activation of the STAT3 pathway, leading to impaired lymphopoiesis by directly affecting hematopoietic stem cells." (PMID 38115705, 2023). "In patients with viral infections, high levels of IL‐18 free have been recognized suggesting the important role of IL‐18 in the cytokine storm, along with IL‐1β and IL‐6, as in the case of COVID‐19." (PMID 36385417, 2023). "Studies using models of acute viral infection suggest that mesenchymal cells are stimulated by interferon-γ to secrete interleukin-6 (IL-6), leading to the expansion of myeloid progenitors and mature myeloid cells." (PMID 36805714, 2023). "On the other hand, although viral infection itself primarily stimulates a lymphocytic response, systemic inflammation, particularly interleukin-6, paradoxically reduces lymphocyte numbers and the resulting cellular immunity." (PMID 37415112, 2023). "The level of IL-6 is closely related to inflammation, viral infection, and other autoimmune diseases." (PMID 37007019, 2023). "These GO-BP terms include well-known host responses against viral infection, such as positive regulation of natural killer (NK) T cell activation, positive regulation of interleukin-6 production and positive regulation of interferon-alpha production." (PMID 36674947, 2023). "During acute viral infection, IL6 activates both Stat1 and Stat3, with the latter being required to limit IL2/Stat5-induced Th1 differentiation." (PMID 37275873, 2023). "Protein concentrations of interferons (IFN-β, IFN-λ, and IFN-γ) and pro-inflammatory cytokines (IL-1β, IP-10, and IL-6) were higher upon virus infection in all cultures." (PMID 37072183, 2023). "We found that both doses significantly reduced the release of inflammatory cytokines (TNFα, IL-6, and IL-1β), induced by virus infection." (PMID 37108306, 2023). "Among these genes, the expression of the inflammatory downstream mediators IL-10, IL-1B, IL-6, and IL-8 was significantly reduced, an interesting finding that was rarely observed in viral infection." (PMID 37134013, 2023).
viral infection (continued). "In particular, they observed increased levels of proinflammatory cytokines IL-6 and TNFα in Peli1 knockout mice upon viral infection." (PMID 37296648, 2023). "To determine and validate the role of temperature on viral infection and IL6/STAT3 signaling, we firstly evaluated the effect of temperature-switch on the immune responses of grass carp tissues or CIK cells." (PMID 37099596, 2023). "In this mouse model, we also show that inflammatory cytokines including IL-6 and KC in the lung of mice are synergistically increased during viral infection after CS exposure." (PMID 36721187, 2023). "IL-6 was measured in models of virus infection (influenza A/H1N1, H1N1) and bacterial infection (lipopolysaccharide, LPS), while IL-5 was measured in an allergen exposure (house dust mite, HDM) model in cell culture supernatants." (PMID 37432355, 2023). "Viral infection induced an inflammatory response (including tumour necrosis factor-α, interleukin [IL]-1β, and IL-6) and an immunomodulatory response (including programmed death-ligand [PD-L]1 and PD-L2)." (PMID 37515098, 2023). "Previous studies show that Ubc9 depletion increases protective IFN1 responses to viral infections, and unleashes massive nearly 6-fold induction of IL6 responses (∼60ng/ml serum) to bacterial endotoxin at 6h post-LPS." (PMID 37520526, 2023). "The mRNA expression of IL-6 and KC in the lung of mice was also synergistically induced by viral infection and CS exposure." (PMID 36721187, 2023). "CH was shown to reduce the secretion and intracellular expression of TNF-α and IL-6, which are inflammatory cytokines that increase after viral infection." (PMID 37711616, 2023). "The circulatory levels of IL-6 increase in several inflammatory states, such as viral infections, septic shock, burns, and trauma." (PMID 37654571, 2023). "Cytokines such as IFN-γ and IL-6 are induced early on after viral infection and are key components of the “cytokine storm”." (PMID 37998327, 2023). "Lastly, we measured the gene expression and protein secretion of IL-6, a cytokine that drives the inflammatory response to viral infections." (PMID 36992456, 2023). "Only the homeostatic IL-6 concentration is effective in settling the tissue lesions and viral infections, on the other hand the excessive IL-6 value progresses towards cytokines storm." (PMID 37756264, 2023). "Conversely, GSH treatment has been found to reduce viral infection and viral load, inhibit pro-inflammatory cytokine production (e.g., IL6, IL8, and TNFα), oxidative stress, and thrombosis, as well as potentially enhance immune function." (PMID 37534078, 2023). "TNF-α, IFN-γ and IL-6, as important proinflammatory cytokines, can help the body fight a viral infection and prevent tissue damage by regulating the inflammatory response." (PMID 37508153, 2023). "IL-6 can play a regulatory role in T cell responses during viral infections by suppressing Th1 differentiation, and promoting pathogen survival while exacerbating clinical disease in SARS-CoV-1 infection." (PMID 37313412, 2023). "Since cytokine and chemokine release modulates responses to bacterial and viral infection, we evaluated the induction of selected interleukin/chemokines, IL-6, IL-8, IFNα and CCL2 mRNA expression following treatment of hfBECs with PAMPS." (PMID 36721242, 2023). "It showed that C. albicans and β-glucan promoted the expression of interferon-β (IFN-β) and interleukin-6 (IL-6) in mouse macrophages triggered by viral infection." (PMID 37243289, 2023). "This cytokine is secreted from Th17 cells and can induce the production of IL-6, IL-8, and several chemokines in response to viral infections, recruiting neutrophils and increasing inflammatory responses." (PMID 37654571, 2023). "At the same time, lower sgp130 that interacts with the IL-6/sIL-6R-complex leads to a decreased block in IL-6 trans signaling, thereby confirming a reduced antagonistic role of sgp130 during the viral infection." (PMID 37887780, 2023).
viral infection (continued). "Expression of pro-inflammatory cytokines, such as Il6 in the early stage of viral infection and Tnf in the late stage of viral infection, were decreased in ivermectin-treated hamsters." (PMID 37185581, 2023). "IL-6 has been shown to play an important role in the host response to many bacterial and viral infections." (PMID 37513733, 2023). "Viral infection triggers an extensive cytokine response, such as IL-1, IL-2, IL-6, TNF-α, IFN-γ, IFN-induced protein 10 kDa and so on." (PMID 38027806, 2023). "Conversely, when WT mice were infected with a genetically modified rabies virus carrying the IL-6 gene, they exhibited greater resistance to viral infection than the parental virus." (PMID 38053527, 2023). "Viral infection dramatically increased the expression of IL-6 and CCL2 in the lungs, while VV116, nirmatrelvir, and combination treatments resulted in a reduction in these cytokines during the initial days." (PMID 37735468, 2023). "The loss of T cells has also been observed in various acute life-threatening viral infections, and the contribution of Fas/FasL and cytokines, such as TNFα, IL-6, IFN-γ, and IL-10, has been suspected." (PMID 38249467, 2023). "TNF-α, IFN-γ, and IL-6, as important proinflammatory cytokines, can help the body fight viral infection and tissue damage by regulating the inflammatory response." (PMID 37764342, 2023). "Numerous investigations through blockage or inhibition of key components of IL6/STAT3 signaling have proven the importance of IL6/STAT3 signaling in virus infection." (PMID 37099596, 2023). "Gal-3BP is a human secreted protein with innate immune functions, which is upregulated in viral infections, promotes inflammation and has been shown to induce IL-6 expression." (PMID 35076790, 2023). "Cytokines, such as IL6 and TNFα, have the ability to enhance immune responses against viral infections/vaccines." (PMID 36851183, 2023). "Their results showed that IL-6 and TNFα were higher in bacterial infections compared to viral infections and elevated cytokine concentrations dropped within three days of antibiotic therapy." (PMID 35500008, 2022). "Previous studies presented high concentrations of CRP, procalcitonin (PCT) and interleukin-6 (IL-6) in bacterial infections compared to viral infections." (PMID 36477474, 2022). "Elevated IL-6 levels have also been linked to patients suffering a CRS exacerbation, suggesting either a viral infection or an altered IL-6 pathway." (PMID 35402317, 2022). "The importance of the IL-1β/IL-6 pathway as a biomarker of trained immunity has also been highlighted in a model of experimental viral infection following yellow fever vaccination." (PMID 35177621, 2022). "Some patients developed a severe disease stage with a cytokine storm, especially the IL-6 production, in their pulmonary tissues approximately one week after viral infection." (PMID 35815275, 2022). "WT infected patients also showed higher IL-17+ CD4+ T cells but with lower IL-4+/IL-6+ CD4+ T cells compared to patients with mutant virus infection." (PMID 34716845, 2022). "Cytokines are crucial in combating viral infection and are involved in the regulation of immune and inflammatory responses, including interleukin 1β (IL-1β), interleukin-6 (IL-6) and tumor necrosis factor alpha (TNF-α)." (PMID 36146669, 2022). "Several articles have described the essential role of IL-6 in generating an adequate immune response during different types of viral infection in the lung tract." (PMID 36615820, 2022). "To achieve our objectives, here we used the human lung epithelial cell line A549 to reproduce: (i) a viral infection resulting in IL-6 cytokine release and (ii) Epithelial–Mesenchymal Transition (EMT) mechanisms resulting in lung fibrosis." (PMID 36671418, 2022). "Interleukin-6 (IL-6) is a strong pro-inflammatory cytokine that plays an important role in the body’s fight against viral infection." (PMID 35664675, 2022).